BECN1 (beclin 1)
Diseases named in the same sentence as BECN1 in open-access papers (continued):
Sharing a sentence is not in itself a finding about the gene and the disease.
intrahepatic cholangiocarcinoma (8 papers, 2013 to 2025). A carcinoma that arises from the intrahepatic bile duct epithelium in any site of the intrahepatic biliary tree. "Here, we detected the clinicopathological and prognostic effect of Beclin 1 in the subtypes of intrahepatic cholangiocarcinoma (ICC) and extrahepatic cholangiocarcinoma (ECC)." (PMID 24303007, 2013). "However, the phenotype of Beclin 1 and its prognostic value in intrahepatic cholangiocarcinoma (ICC) as well as extrahepatic cholangiocarcinoma (ECC) were unclear." (PMID 24303007, 2013). "In addition, we employed multiplex immunofluorescence (mIF) staining to detect the expression of key autophagic markers, including Beclin-1, p62, and LC3B, in intrahepatic cholangiocarcinoma (ICC) tumor vasculature." (PMID 39744218, 2025).
osteoporosis (8 papers, 2019 to 2024). A condition of reduced bone mass, with decreased cortical thickness and a decrease in the number and size of the trabeculae of cancellous bone (but normal chemical composition), resulting in increased fracture incidence. "The present study experimentally demonstrated the effect of Beclin-1/Bcl-2 on osteoblasts, which provided new ideas and theoretical basis for understanding the pathogenesis of osteoporosis." (PMID 39834809, 2024). "The Beclin-1/Bcl-2 complex plays a pivotal role in regulating both autophagy and apoptosis in osteoblasts affected by osteoporosis." (PMID 39834809, 2024). "Revealed by the western blot results, there was a significant decreased expression of LC3 and Beclin-1 in osteoporosis group when compared with the normal control group." (PMID 31804494, 2019). "Therefore, reducing the Beclin-1/Bcl-2 complex ratio in osteoblasts enhances autophagy and reduces apoptosis, which is a potential new option for the treatment of osteoporosis." (PMID 39834809, 2024). "However, there is limited research on the role of the Beclin-1/Bcl-2 complex in osteoblasts in the context of osteoporosis." (PMID 39834809, 2024). "Moreover, Western bolt analysis showed that expression of SIRT1, LC3, and Beclin-1 in osteoblasts increased, while p-AKT and p-mTOR were downregulated in osteoporosis rats with high dose resveratrol treatment." (PMID 31804494, 2019). "While in osteoporosis with high dose resveratrol treatment, the expression of LC3 and Beclin-1 protein were significantly increased, indicating that resveratrol may induce autophagy of bone cells." (PMID 31804494, 2019).
pancreatic ductal adenocarcinoma (8 papers, 2013 to 2024). An infiltrating adenocarcinoma that arises from the epithelial cells of the pancreas. "In contrast, Beclin 1 was significantly correlated with short disease-free survival and overall survival of pancreatic ductal adenocarcinoma." (PMID 33425768, 2020). "Similarly, increased Beclin-1 expression was closely correlated with the absence of local lymphatic invasion and low rate of distant metastasis for pancreatic ductal adenocarcinoma." (PMID 24303007, 2013).
cystic fibrosis (7 papers, 2013 to 2021). Autosomal recessive disorder caused by pathogenic variants in the CFTR gene (cystic fibrosis transmembrane conductance regulator), which encodes a chloride and bicarbonate channel expressed in epithelial cells, and follow the diagnosis criteria. "However, the autophagy pathway has been shown to be impaired in cystic fibrosis patients by mutations in CFTR which lead to dysregulation of the beclin-1 PI3K complex." (PMID 24015228, 2013). "Cysteamine normalizes the proteostasis machinery by restoring BECN1/Beclin 1-dependent autophagy in cystic fibrosis in mouse models of the disease and also in patients." (PMID 31920936, 2019). "CF is characterized by mutations in cystic fibrosis transmembrane conductance regulator (CFTR), a chloride channel whose malfunction triggers the activation of transglutaminase-2 (TGM2), as well as the inactivation of the Beclin-1 (BECN1) complex resulting in disabled autophagy." (PMID 31321000, 2019). "During lung inflammation in cystic fibrosis, CTM restored TG2-mediated crosslinking of beclin 1 and subsequently rescued defective autophagy, aggresome formation, and the CF airway phenotype." (PMID 33672962, 2021).
glaucoma (7 papers, 2013 to 2024). Increased pressure in the eyeball due to obstruction of the outflow of aqueous humor. "In addition, we also quantitatively analyzed both groups for the expression of apoptosis-related (BAD, BAX, BCL2L10, and XIAP) and autophagy-associated (HAX1 and Beclin-1) marker proteins, since both signaling cascades are supposed to be highly involved in the molecular pathogenesis of glaucoma." (PMID 36313990, 2022). "It has been verified that BECN1, a core autophagy modulator, has a close correlation with autophagy in retinal ischemia, DR, and glaucoma." (PMID 37522124, 2023). "NS+/+Tg mice demonstrated decreased PSD95, beclin-1, LC3-II/LC3-I ratio, and IBA1 following glaucoma induction, highlighting its protective role." (PMID 36905120, 2023). "We observed significantly elevated levels of beclin-1 (control, p < 0.02; glaucoma, p < 0.03) and LC3BII/I markers (control, p < 0.03; glaucoma, p < 0.007) in retinas under control and experimental glaucoma conditions." (PMID 36905120, 2023). "Beclin-1 and the LC3B-II to LC3B-I ratio significantly elevated at 4 and 8 weeks after glaucoma induction; however, only a slight increase was apparent in the diabetic retina." (PMID 30190527, 2018). "WB analysis of the retinal tissues showed that the autophagy markers beclin 1 (p < 0.03) and LC3B-II/I (p < 0.03), which are enhanced under glaucoma conditions, were significantly decreased in the AAV-NS-treated glaucoma group (p < 0.007 and p < 0.005 respectively)." (PMID 36905120, 2023). "WB analysis of retinal tissues showed that the autophagy markers beclin 1 (p < 0.03) and LC3B-II/I (p < 0.05) were enhanced under glaucomatous conditions and significantly decreased in AAV-NS-treated experimental glaucoma mice (p < 0.006 and p < 0.009, respectively)." (PMID 36905120, 2023). "However, baicalin treatment attenuated the EIOP-induced increase in protein expression of LC3-II, Beclin-1, and ATG5 in Model+NS group, which indicated that baicalin inhibited autophagy in glaucoma progression." (PMID 34860641, 2021). "Chronic elevation of IOP in glaucoma triggers a gradual increase in beclin-1 and LC3B-II in the absence of AMPK involvement." (PMID 30190527, 2018). "WB examination of retinal lysates revealed that, while beclin 1 expression was only affected under glaucoma conditions and was reduced compared with WT mice (p < 0.05), LC3BII/I was relatively reduced in NS+/+ Tg retinas under control (p < 0.05) and experimental glaucoma conditions (p < 0.009)." (PMID 36905120, 2023).
lupus (7 papers, 2016 to 2023). "In LN, the renal tissue of lupus mice and the serum of lupus patients exhibit atypically high levels of autophagy and autophagy markers, like programmed cell death-1 (Beclin-1)." (PMID 37894915, 2023). "The autophagy-related genes (Atg5, Atg12 and Beclin 1) were significantly upregulated in the splenic and renal macrophages in activated lymphocytes-derived DNA (ALD-DNA) induced lupus mice and in the peripheral blood mononuclear cells from SLE patients." (PMID 36865559, 2023). "The expression of HOXA11-OS, Cyr61, and the autophagy factors Beclin-1 and LC3B in the kidney tissue of lupus mice and serum of lupus patients was detected by qRT-PCR and western blotting." (PMID 36418932, 2022). "Lower levels of Beclin 1 and LC3-II/LC3-I and higher levels of p62 were observed in the lupus group compared to the normal control group, which indicated that autophagy was inactivated in the lupus group." (PMID 34721589, 2021). "Compared to the lupus group, the ADSC group showed lower p62 expression and higher Beclin 1 and LC3-II/LC3-I expression (P < 0.05), and the miR-20a group had a much stronger effect on inducing autophagy compared with the ADSC group (P < 0.05)." (PMID 34721589, 2021). "It has been reported that decreased levels of Beclin-1, mTOR, and LC3-II are detected in lupus patients." (PMID 28035990, 2016). "LC3 amplifies the response to intracellular DNA, and another important member of the autophagy pathway, Beclin-1, serves as an inhibitor, thereby suppressing IFN-α production, a key effector cytokine in lupus pathogenesis." (PMID 28035990, 2016).
malignant glioma (7 papers, 2016 to 2025). A grade III or grade IV glioma arising from the central nervous system. "This definition is underpinned by the clinical observation that a high tissue expression of cytoplasmic Beclin-1 was related to better prognosis in patients with malignant glioma on temozolomide chemotherapy and radiotherapy." (PMID 34445095, 2021). "The expression of LC3-II and LAMP-1 in malignant glioma cells are rescued by si BECN1 following treatment with TGF-β1 (5 ng/ml) for 24 hours." (PMID 26909607, 2016). "More importantly, Beclin-1 played a role in autophagy and functioned as a tumor suppressor in malignant glioma cells." (PMID 26824182, 2016). "IRT triggered the accretion of autophagosomes as well as the radiosensitizing effect of autophagy‐related BECN1/BECLIN1 deficiency, leading to the disruption of nuclear translocation and Ku protein activity, resulting in the mitigation of DSB repair in malignant glioma." (PMID 41498028, 2025). "To explore whether BECN1 is involved in TGF-β1-induced malignant glioma cell autophagy, we examine the effect of siRNA BECN1 on malignant glioma cell autophagy." (PMID 26909607, 2016).
metabolic syndrome (7 papers, 2012 to 2025). A cluster of metabolic risk factors for CARDIOVASCULAR DISEASES and TYPE 2 DIABETES MELLITUS. "In the current study, we identified an exaggerated expression of autophagy molecular markers p62, LC3, and BECN-1 mRNA in the aortic tissue sample of the metabolic syndrome group compared to the control group in addition to the appearance of autophagosomes by electron microscopic examination." (PMID 39610878, 2024).
non-Hodgkin lymphoma (7 papers, 2014 to 2021). Distinct from Hodgkin lymphoma both morphologically and biologically, non-Hodgkin lymphoma (NHL) is characterized by the absence of Reed-Sternberg cells, can occur at any age, and usually presents as a localized or generalized lymphadenopathy associated with fever and weight loss. "The positive expression of Beclin-1 in non-Hodgkin lymphomas correlates with the presence of LC3-positive autophagic vacuoles." (PMID 25202355, 2014). "With relevance to our findings, a previous study showed that high expression of Beclin-1 correlated with a good prognosis in non-Hodgkin lymphoma when the tumors were Bcl-2 low or negative expressing and positive for the autophagy marker LC3." (PMID 24885292, 2014).
oral squamous cell carcinoma (7 papers, 2018 to 2025). "However, the data regarding the association between the role of Beclin-1 and the progression of Oral Squamous Cell Carcinoma (OSCC) are rather low." (PMID 34769649, 2021). "Our previous study revealed that 16-hydroxy-cleroda-3,13-dien-16,15-olide (HCD) and PG activated Beclin-1 independent autophagy and led to oral squamous cell carcinoma cell death." (PMID 30282915, 2018).
astrocytomas (6 papers, 2014 to 2021). "In the present study, protein expressions of LC3B and Beclin-1 in astrocytoma patients were evaluated and the results were utilized to correlate with clinical parameters." (PMID 24900981, 2014). "The purpose of the present study was to assess the relationship between protein expressions of two autophagy markers, LC3B and Beclin-1, with clinical parameters in astrocytoma patients." (PMID 24900981, 2014). "The quantification of p62, LC3B, Beclin-1 and BAG3 (autophagosomal molecules) proved that nutrient or oxygen deprivation enhances the autophagy in astrocytoma compared to normal brain tissue." (PMID 33525678, 2021). "Pathological studies have shown that the levels of Beclin 1 and LC3-2, biomarkers of autophagy, are lower in GBMs relative to lower-grade astrocytomas, as well as normal brain tissue." (PMID 31870319, 2019). "On the other hand, low levels of Beclin 1 and the LC3-II protein have been found in higher-grade astrocytomas, suggesting that a decrease in autophagic activity may drive the progression of astrocytic tumors." (PMID 31870319, 2019). "The results of immunohistochemical staining of Beclin-1 and LC3B were separately analyzed to determine the relationship of protein expression with clinicopathological parameters of astrocytoma patients, such as age, gender, tumor grade, resistance to radiation- or chemotherapy, and KPS scale." (PMID 24900981, 2014).
Cachexia (6 papers, 2011 to 2022). Severe weight loss, wasting of muscle, loss of appetite, and general debility related to a chronic disease. "Severely cachectic MIN mice have increased muscle Beclin‐1 and LC3B expression, suggesting that more severe cachexia is associated with higher autophagy–lysosome system activity." (PMID 34270178, 2021). "The expression of autophagy-related proteins Beclin-1, Atg7 and LC3B increased approximately 2-fold during the progression of cachexia in untreated mice (P<0.001)." (PMID 21949739, 2011). "In gastrocnemius of mice with the two conditions (LC-cachexia and unloading), levels of the markers beclin-1, p62, LC3-II/I protein, and cleaved caspase-3 did not significantly differ among the study groups." (PMID 33142912, 2020). "Compared to unloaded (7-day I and 15-day I) animals, in mice with the two conditions (LC-cachexia and unloading), beclin-1, p62, LC3-II/I, and cleaved caspase-3 protein levels did not significantly differ, while LC3-II/I levels (only in LC 30-days + 15-day I) significantly increased (+80% change)." (PMID 33142912, 2020). "Here we demonstrated that both sorafenib and regorafenib induced elevations in Beclin 1 and LC3-II/I in skeletal muscle, thus supporting the idea that autophagy activation may trigger muscle depletion in our experimental model, similar to previous findings in a cancer cachexia setting." (PMID 31018508, 2019). "Protein levels of beclin-1 and LC3B were significantly greater in the gastrocnemius and diaphragm (p = 0.08, beclin-1) of cancer cachexia mice than in the non-cachectic controls, and treatment with rucaparib significantly reduced those levels in the cachectic animals (respectively)." (PMID 35740560, 2022).
embryonal carcinoma (6 papers, 2014 to 2024). A non-seminomatous malignant germ cell tumor characterized by the presence of large germ cells with abundant cytoplasm resembling epithelial cells, geographic necrosis, high mitotic activity, and pseudoglandular and pseudopapillary structures formation. "Moreover, this study provided a link between embryonal carcinoma stem cell differentiation following PHGDH inhibition and the induction of Beclin-1 dependent autophagy and senescence of embryonal carcinoma stem cells." (PMID 33801846, 2021).
endotoxemia (6 papers, 2019 to 2023). "Data showed that endotoxemia decreased both the total mass and the function of MAMs, and these deficiencies became worse in Becn1+/− mice but were alleviated in Becn1‐Tg and TB‐peptide‐treated mice." (PMID 33733054, 2021). "Enoxaparin administration substantially alleviated the enhanced expression of calpain, atrogin-1, MuRF-1, LC3-II, and Beclin-1 caused by endotoxemia and MV at VT = 10 mL/kg." (PMID 33567713, 2021). "Overall, these observations suggest that LPS induces deficiencies in cardiac MAMs, and Beclin‐1 is able to control this deterioration process during endotoxemia." (PMID 33733054, 2021). "Our recent published study revealed that Beclin-1 supports the function and quantity of mitochondria-associated membranes (MAMs), a subcellular domain bridging mitochondria and ER, in the heart under the pathological condition of endotoxemia." (PMID 36875088, 2023). "It further suggests that, under both physiological condition and physiological condition of endotoxemia, Beclin‐1 signaling is required to retain lipid levels in the heart, which is likely at least one of the mechanisms underlying Beclin‐1‐dependent support of MAMs." (PMID 33733054, 2021). "In fact, specific activation of Beclin-1, either genetically or pharmacologically, significantly improves cardiac performance under the challenge of endotoxemia." (PMID 36875088, 2023). "Our previous investigation in a mouse model of endotoxemia demonstrated that Beclin-1 possesses the capability to prevent mitochondrial structural damage, trigger adaptive mitophagy, and thus reduce the amount of free mtDNA in myocardium." (PMID 36875088, 2023). "We previously found that the promoting autophagy via autophagy initiation factor Beclin-1 limited inflammation, governed mitochondrial quality control, reduced mitochondria-derived DAMPs, and thus, improved cardiac function during endotoxemia." (PMID 35265609, 2022). "Our recent study further revealed that targeted activation of Beclin-1, either genetically or pharmacologically, is capable of protecting the structure and function of cardiac MAMs from endotoxemia challenge." (PMID 35265609, 2022). "One of our ongoing investigations is aimed at determining the potential signaling pathway between Beclin‐1 and Mfn2 in cardiac MAMs and the responses of these signaling components to endotoxemia." (PMID 33733054, 2021). "These in vitro data confirmed what was observed in vivo, showing that the activation of the Beclin‐1 pathway preserved MAMs in myocardium in response to endotoxemia." (PMID 33733054, 2021). "Total calpain, atrogin-1, MuRF-1, LC3-II, and Beclin-1 levels were higher in mice with endotoxemia subjected to VT = 10 mL/kg than in mice in the other MV treatment groups and the non-ventilated control mice." (PMID 33567713, 2021). "We detected that the specific activation of Beclin‐1 improves cardiac function and limits myocardial inflammation during endotoxemia." (PMID 33733054, 2021). "Recently, our investigation showed that the targeted activation of the autophagy initiation factor Beclin‐1 improves the quality control of mitochondria in the heart tissue and sequentially attenuates cardiac dysfunction in response to endotoxemia." (PMID 33733054, 2021). "Together, the results suggest a new function of Beclin‐1 in improving cardiac MAMs during endotoxemia, providing a mechanism for the previously identified role of Beclin‐1 in protection of mitochondria and cardiac function." (PMID 33733054, 2021). "Our laboratory recently investigated the role of Beclin‐1 in the heart during endotoxemia induced by lipopolysaccharide (LPS), a major molecule of pathogen‐associated molecular patterns released from gram‐negative bacteria." (PMID 33733054, 2021). "Recently, we discovered that enhancing Beclin‐1‐dependent autophagy attenuates mitochondrial damage in the heart during endotoxemia." (PMID 33733054, 2021).